BRAF (B-Raf proto-oncogene, serine/threonine kinase)
Diseases named in the same sentence as BRAF in open-access papers (continued):
Sharing a sentence is not in itself a finding about the gene and the disease.
melanoma (continued). "Also, the hyperactivation of MAPK signaling increases reactive oxygen species (ROS) levels in BRAF inhibitor-resistant melanoma cells, and histone deacetylase inhibitor vorinostat boosts ROS levels, selectively killing drug-resistant tumor cells." (PMID 40141318, 2025). "This study showed the development of a model spanning multiple lines of treatment to estimate the long-term health benefits of treatments and treatment sequences for patients with advanced melanoma with and without a BRAF mutation." (PMID 39985400, 2025). "This may suggest that the clinical benefit of ICI before targeted therapy, seen in BRAF mutant melanoma, may be replicated in other tumour types or oncogenic drivers." (PMID 40362630, 2025). "Analysis of differential MEs revealed module 14 (TLCD2, PRICKLE2-AS3, and SPN) was significantly upregulated by NRAS Q61L melanomas (log2fc = 100.2, adjusted p = 1.32 × 10−2) and downregulated by BRAF V600E melanomas (log2fc = −206.3, adjusted p = 3.51 × 10−14)." (PMID 39796775, 2025). "In melanoma cells, it has been shown that a v-Raf murine sarcoma viral oncogene homolog B1 (BRAF)- mitogen-activated protein kinase kinase (MEK) inhibitor agent can induce pyroptosis by triggering GSDME, leading to elevated T-cell infiltration and immune system responses." (PMID 41291696, 2025). "In addition, preclinical studies have demonstrated that autophagy can contribute to resistance to targeted therapy in models of BRAF-mutant melanoma." (PMID 40457397, 2025). "Regarding this observation, early evidence on sequentiality indicated that ICI first could reach better outcomes than BRAF/MEK inhibitors in advanced melanoma." (PMID 40078188, 2025). "In addition, recent studies have shown that in BRAF-mutant melanoma, aberrant ALK activation can restore MAPK pathway signaling through bypass mechanisms, conferring resistance to BRAF inhibitors (BRAFi)." (PMID 40873540, 2025). "This may be MAPK-driven, as increasing accumulation of CD68+ and CD163+ microglia is similarly observed in melanoma, correlating with greater tumour size and Breslow depth, and at significantly higher levels in BRAF-altered samples." (PMID 39948623, 2025). "Monomeric GTPases such as Rac1 are activated by guanine exchange factors (GEFs), and we previously identified upregulated DBL family member GEFs, including Vav1, as drivers of resistance to BRAF inhibitors (BRAFi) in a forward genetic screen using BRAF-mutant melanoma cells." (PMID 41109929, 2025). "Similarly, another study suggested that antibiotic use was associated with reduced TKI efficacy in advanced melanoma and NSCLC, but the TKI cohort also included both EGFR and BRAF inhibitors, precluding class-specific conclusions." (PMID 41294692, 2025). "Vemurafenib (Zelboraf®) and Dabrafenib (Tafinlar®) are available small-molecule inhibitors targeting the BRAF V600E mutation, demonstrating significantly improved overall survival rates without similar efficacy against the wild-type melanomas." (PMID 39795195, 2025). "Twenty-two percent of skin and 2% of mucosal, but not uveal, melanomas harbored actionable BRAF V600E/K variants." (PMID 39823560, 2025). "In addition, the BRAF inhibitors in combination with MEK inhibitors have been established as the standard adjuvant and neoadjuvant therapy for malignant melanoma with BRAF V600E mutations based on high-level clinical evidence." (PMID 41480531, 2025). "BRAF and NRAS mutations are common pathogenic mutations in melanoma." (PMID 40933889, 2025). "Aberrations in the reactivated MAPK pathway, such as genetic alterations of RAS and MEK, BRAF amplification, loss of NF1, deregulation of COT1, and BRAF alternative splicing, are frequently detected in melanoma progression despite treatment." (PMID 40681872, 2025).
melanoma (continued). "Notably, dual HDAC/BRAFV600E inhibitors based on the chemical structures of sorafenib and dabrafenib were meanwhile disclosed with higher antiproliferative activity against BRAFV600E-mutant cells (melanoma or CRC cells) compared with BRAF-wildtype cells." (PMID 39935431, 2025). "Of note, although the combination of dabrafenib (BRAFi) and trametinib (MEKi) is an established clinical treatment for BRAF-mutant melanoma due to its improved efficacy and delayed resistance, we employed single-agent treatments in our models to dissect their specific resistance mechanisms." (PMID 40943167, 2025). "Moreover, the expression and nuclear accumulation of cyclin D1 and p21 were also suppressed in AZD6244-treated BRAF PTEN PREX2 melanomas (right)." (PMID 39636745, 2025). "Thus, drug-resistant BRAF-mutant melanoma developed a specific sensitivity to HDAC inhibitor therapy, which was also clinically verified." (PMID 39935431, 2025). "Melanoma shows particular sensitivity to copper toxicity due to its metabolic characteristics: 35%–50% of wild-type, BRAF-mutant, and patient-derived melanoma cells rely heavily on oxidative phosphorylation (OXPHOS) for energy, making them sensitive to copper-induced mitochondrial damage." (PMID 41170386, 2025). "Furthermore, certain polyamine-related drugs can also mitigate tumor drug resistance; for example, the combination of a novel arylmethyl-polyamine (AP) with the BRAF inhibitor (PLX4720) significantly delays recurrence in PLX4720-resistant melanoma." (PMID 40040695, 2025). "Regardless, neoadjuvant BRAF-targeted therapy remains a valid, guideline endorsed treatment option for patients with clinical stage III, BRAF-mutated melanoma and may be offered as an alternative to ICI therapy." (PMID 40857557, 2025). "Targeted therapies, including BRAF and MEK inhibitors, are considered in BRAF-mutant melanoma." (PMID 40236344, 2025). "Furthermore, renin–angiotensin system inhibitors potentiate the effect of BRAF and MEK inhibitors in BRAFV600-mutated melanoma cells." (PMID 39941158, 2025). "Aside from representing distinct cancers, the AML cell lines differ from the A375 melanoma line insofar as both MV4–11 and HL-60 cells are BRAF wildtype, whereas A375 cells possess the BRAF V600E mutation, the oncogenic driver mutation for which Trm most commonly is used clinically." (PMID 40964318, 2025). "Both BiTEs and ADCs may benefit from combination strategies with other melanoma treatments, such as immune checkpoint inhibitors or targeted therapies, like BRAF and MEK inhibitors." (PMID 39857682, 2025). "The aim of this study was to investigate whether there are dermoscopic differences between BRAF-mutated and BRAFWT melanomas and whether dermoscopy can help differentiate between melanomas in situ (stage 0) and invasive thin melanomas (Breslow index ≤ 1 mm)." (PMID 41010758, 2025). "In melanoma, senescence may arise as a result of oncogenic BRAF or NRAS activation, therapeutic stress, or immune‐mediated signals." (PMID 40926366, 2025). "In addition to melanoma, ribociclib with encorafenib have synergistic cytotoxic effects in BRAF-mutant colorectal cancer." (PMID 39948552, 2025). "Small-molecule inhibitors of BRAF (vemurafenib, dabrafenib, encorafenib) were developed and first studied in BRAF V600-mutant melanoma, demonstrating impressive overall response rates (ORRs) but short progression-free survival (PFS) due to rapid MAPK-pathway reactivation." (PMID 41294686, 2025). "Retained p16 expression with a negative result in the BRAF V600E mutations have lower levels of FISH chromosomal abnormalities related to melanoma in comparison to the expression loss of p16." (PMID 40870546, 2025).
melanoma (continued). "To understand whether the mechanisms associated with delayed onset of resistance in the BRAF PTEN model of melanoma aligned to those identified in vitro, we analyzed the expression patterns of key biomarkers in BRAF PTEN melanomas in vivo." (PMID 39636745, 2025). "This evidence suggests that targeting resistance mechanisms mediated by TKRs through ALW-II-41-27 or other multikinase inhibitors could represent an effective therapeutic strategy to overcome resistance in metastatic BRAF-mutant melanoma." (PMID 40872623, 2025). "TAMs, in turn, protect melanoma cells from apoptosis induced by the BRAF inhibitor vemurafenib." (PMID 40058234, 2025). "Furthermore, it indicates the need for adjuvant therapies with immune checkpoint inhibitors or targeted therapies in BRAF-mutant melanoma." (PMID 40282456, 2025). "In contrast, ddPCR methods are far more economical, but the mutational profile must be known in advance, and >20% of melanoma patients do not harbor a known driver genomic alteration, which are known to be BRAF and NRAS-wt." (PMID 39859576, 2025). "However, in approximately 30% of melanoma cases that are wild-type (wt) for both BRAF and NRAS, ctDNA analysis is more challenging." (PMID 39859576, 2025). "The only patient with a KIT mutation developed delayed-onset brain metastases, while no patients with quadruple negative melanoma (lacking mutations in BRAF, NRAS, NF1, or KIT) developed CNS involvement." (PMID 41301010, 2025). "Furthermore, in patients with advanced unresectable melanoma who had either progressed on ipilimumab or a BRAF or MEK inhibitor (if BRAFV600E/K mutant), pembrolizumab reduced the risk of disease progression as compared with the standard‐of‐care chemotherapy." (PMID 40635600, 2025). "This Pik3cb mutant had little-to-no impact upon disease trajectory, with naevus onset and melanoma initiation similar to BRAF PTEN controls, although Pik3cb mutation did seem to result in improved overall survival." (PMID 39636745, 2025). "One explanation could be a fundamentally higher aggressiveness of BRAF-mutant melanomas, which has been described in several studies conducted prior to the introduction of targeted tumor therapy." (PMID 40028330, 2025). "Mutations of the BRAF gene can cause BRAF phosphorylation and activation of MEK proteins (MEK 1 and MEK 2), thereby causing sustained activation of the downstream MEK-ERK signaling pathway, exacerbating melanoma growth, proliferation, invasion, and metastasis." (PMID 41155918, 2025). "Thus, the combination of HDAC inhibition with BRAF inhibition can break the resistance of NK cells to melanoma cells." (PMID 39935431, 2025). "Targeted therapies are available for patients with melanomas expressing BRAF mutations; however, responses are not durable for most patients." (PMID 39753970, 2025). "We concentrated on melanoma lines that do not have a mutation in BRAF, since there are adequate second-line therapies available for BRAF mutant melanoma patients, but not for BRAF wild-type melanoma patients." (PMID 40904502, 2025). "From melanoma to rare cancers, we highlight how BRAF has become a paradigm of precision oncology." (PMID 40332392, 2025). "Importantly, we observed similar ECM signatures in human melanoma datasets from patients treated with BRAFi or BRAF/MEKi, suggesting that therapy‐induced ECM alterations are a conserved and clinically relevant response." (PMID 40847444, 2025). "This mutation leads to the constitutive activation of the mitogen-activated protein kinase (MAPK) signaling pathway, resulting in uncontrolled cell growth and proliferation, thus BRAF mutants has been designated as a crucial drug target for the treatment of melanoma." (PMID 41355975, 2025). "Therefore, combining autophagy inhibition with BRAF inhibition enhanced the anticancer effect on melanoma xenografts using BRAF inhibitor-resistant melanoma." (PMID 41155168, 2025).
melanoma (continued). "Furthermore, following 24-hour treatment with trametinib + dabrafenib, the MEK and BRAF inhibitors that are the standard-of-care treatment for melanoma, A375s increase their expression of Axl while decreasing their shedding of the receptor." (PMID 40539073, 2025). "This mutation-specific metabolic rewiring highlights how ketogenic diets could be detrimental in the context of BRAF V600E melanoma, emphasizing the need for personalized dietary and therapeutic strategies." (PMID 40565936, 2025). "However, another study from the same investigators found that BRAF-MEK-CDK4/6i combined with adoptive cell transfer (ACT) led to a sustained antitumor response in a BRAFi-sensitive murine model of melanoma." (PMID 40282469, 2025). "Under BRAF inhibitor treatment, BRAF-V600E melanoma cells become dependent on OXPHOS for survival." (PMID 39501277, 2024). "Thereafter, approval of adjuvant therapy for stage III melanoma with anti-PD-1 antibodies, pembrolizumab and nivolumab, regardless of the tumor BRAF mutational status, opened to additional treatment possibilities." (PMID 39148899, 2024). "A recent study suggests that cytokine IL-6 could be the biomarker of disease progression and poor prognosis in BRAF wild-type advanced melanoma treated with pembrolizumab." (PMID 39195270, 2024). "Recently, molecular genetic analysis has shown that malignant melanoma is closely related to BRAF." (PMID 38335433, 2024). "BRAF-mutant CoM exhibits a more aggressive clinical behaviour compared to BRAF wild-type melanomas." (PMID 39055896, 2024). "In non-V600 BRAF mutant melanoma, trametinib ± dabrafenib exhibited some efficacy." (PMID 38333370, 2024). "A later report on this trial involved 153 melanoma patients with ICI- or BRAF/MEK-resistant disease; treatment with lifileucel was associated 1-, 2-, 3- and 4-year os rates of 53%, 33.9%, 28.4% and 21.9% and with an ORR of 31.4%, with the median duration of response not reached." (PMID 39727691, 2024). "The viability of the detached melanoma cells in adherent cultures was, however, significantly and positively influenced by the presence of neutrophils, thereby restoring the protective effect against dual BRAF/MEK inhibition." (PMID 38730718, 2024). "Interestingly, a pilot study found that in BRAF + MEK inhibitor-resistant melanoma, chemotherapy can be a successful treatment modality if it induces pyroptosis, an immunogenic form of cell death." (PMID 39272837, 2024). "We report a previously unrecognized signaling mechanism supporting drug tolerance in BRAF-mutant melanoma treated with BRAF inhibitors that could be of general relevance to other cancers." (PMID 39001489, 2024). "Out of 86 patients diagnosed with BRAF-mutant melanoma (52.8%), 81 were treated with TT (94.2%)." (PMID 39272953, 2024). "Additionally, targeted therapy with BRAF-/MEK-inhibitors increases survival in BRAFV600mutant melanoma." (PMID 39314226, 2024). "Alternatively, combining CSPG4-CAR T cells with conventional treatments for melanoma, like BRAF and MEK inhibitors (BRAFi/MEKi), may provide a further treatment strategy." (PMID 39409881, 2024). "Notably, dietary intake of glutamine has proven effective in slowing melanoma growth, prolonging survival, and increasing responsiveness to BRAF inhibitor therapy." (PMID 39403606, 2024). "Studies also show that HDACi may sensitize melanoma cells to immunotherapy and targeted therapy and hence may be combined with immune checkpoint blockade or BRAF and MEK inhibition." (PMID 39494561, 2024). "BRAF acts downstream of RAS and is frequently mutated in cancers like melanoma." (PMID 38310289, 2024). "Determination of BRAF V600 status is mandatory in patients with stage IV melanoma." (PMID 38748192, 2024). "These vaccines have demonstrated encouraging results in early-phase trials across various cancers and could significantly enhance immune responses in patients with BRAF-mutant melanoma when used alongside other therapeutic modalities." (PMID 39336897, 2024).
melanoma (continued). "Accordingly, BRAF-mutated soft-tissue sarcomas are often mistaken for metastases of dedifferentiated (nonpigmented) melanoma." (PMID 39018206, 2024). "Moreover, a combination of an eIF4F inhibitor with vemurafenib and cobimetinib prevented the emergence of persister melanoma cells that can tolerate the exposure to lethal concentrations of the BRAF and MEK inhibitors." (PMID 39436655, 2024). "For instance, PERK has been found to be essential to the progression of BRAF-mutated melanoma but has less of a role in non-BRAF mutated tumors." (PMID 38732072, 2024). "In this retrospective, single-center, case series, we show that combining the multi-kinase inhibitor regorafenib with standard-of-care BRAF/MEK inhibitors can have meaningful anti-tumor activity in melanoma patients with progressive MBM with an acceptable safety profile." (PMID 39682270, 2024). "Driver mutations of a conventional melanoma, such as BRAF, NRAS, or NF1, should not be seen in the Spitz family." (PMID 38247727, 2024). "Patients with advanced BRAF-mutated melanoma treated with first-line immunotherapy had a significantly longer PFS and OS than those treated with first-line BRAF/MEKi; however, first-line BRAF/MEKi treatment had a significantly higher ORR than first-line immunotherapy." (PMID 38450188, 2024). "For patients with locoregional advanced melanoma that can be treated with complete resection, adjuvant—and more recently neoadjuvant—with targeted therapy—BRAF and MEK inhibitors—and immunotherapy—anti-PD-1-based therapies—offer opportunities to reduce the risk of relapse and distant metastases." (PMID 38748192, 2024). "Interestingly, OXPHOS inhibitors or mitochondrial uncouplers have been shown to be sensitive to vemurafenib in BRAF-mutant melanoma cell lines." (PMID 38790264, 2024). "However, it is important to note, that melanoma cells differ in terms of the features that appear in connection with the acquisition of resistance to BRAFi monotherapy and a mixture of BRAF/MEK inhibitors." (PMID 39175042, 2024). "that regardless of PD-1 ligand expression level and BRAF mutation status, pembrolizumab has been found to be associated with longer progression-free survival and overall survival in melanoma." (PMID 38988710, 2024). "Therefore, there is an immediate need to develop innovative and effective combination therapies for advanced BRAF-mutant melanoma." (PMID 38594618, 2024). "Additionally, they also inhibited the proliferation of BRAF mutant A-375 melanoma cells with IC50 values of 3.7 and 0.13 μM." (PMID 38686058, 2024). "Likewise, enrichment of c-Myc and mitochondrial OXPHOS related genes are also found in BRAF mutant melanoma with intrinsic resistance." (PMID 38965534, 2024). "Moreover, there are no studies on pseudogene transcripts alteration depending on the BRAF gene status in melanoma." (PMID 39764216, 2024). "As relates to the targeted therapy use of BRAF inhibitors (if there is a BRAF mutation), this represents the standard care for metastatic melanoma both for melanomas associated with sun exposure or with lack of such association." (PMID 38927967, 2024). "This figure outlines personalized therapy pathways in BRAF-mutant melanoma." (PMID 39336897, 2024). "Previous studies identified extrachromosomal DNA (ecDNA) events in melanoma that affect the BRAF and NRAS locus, and therefore we determined whether any intrachromosomal chromothripsis events spanning these loci were actually ecDNA amplifications." (PMID 38758740, 2024). "Furthermore, we demonstrated that pharmacological MAP3K3 inhibition can overcome YAP-induced resistance to CDK4/6 inhibitors in breast cancer cells and to BRAF inhibitors in melanoma cells, underscoring the therapeutic relevance of our findings." (PMID 38622197, 2024). "Loss of PTEN in melanoma may therefore increase levels of IGFBP2 and, we hypothesize, impact the standard of care (BRAF/MEK inhibition) for melanoma cells." (PMID 39007351, 2024).